TNF (tumor necrosis factor)
Diseases named in the same sentence as TNF in open-access papers (continued):
Sharing a sentence is not in itself a finding about the gene and the disease.
lung carcinoma (continued). "Treatment with tumor necrosis factor-alpha (TNF-α) enhanced apoptosis in SAHA-treated lung cancer cells through caspase-8 and caspase-9 activations." (PMID 28099148, 2017). "For exmple, SIRT1 was reported to be a tumor promoter in lung adenocarcinoma and can enhance β-catenin accumulation then to activate TNF-α transcription, leading to sustained inflammation and lung cancer development." (PMID 28977967, 2017). "We measured and compared 1170 protein phosphorylation events in a panel of human lung cancer cell lines based on different signals, subcellular regions, and time points within one hour of TNFα treatment." (PMID 28272488, 2017). "MSCs significantly augmented lung cancer metastasis, attenuate concentrations of proinflammatory cytokines (TNF-α, IL-17), and increase levels of immunosuppressive IL-10, nitric oxide, and kynurenine in sera of LLC1-treated mice." (PMID 28798777, 2017). "Tumor necrosis factor α and IL-1α were also reported to be released in H446 lung cancer cells after irradiation with γ-rays (8 Gy), but only TNF-α after irradiation with accelerated carbon ions (290 MeV/n, LET 13 keV/μm, 2 Gy)." (PMID 28638385, 2017). "Both TLR2 and TLR6 signaling can promote lung cancer progression by inducing tumor necrosis factor-α (TNF-α) production of macrophages." (PMID 28241846, 2017). "We found that the frequency of TNF-α production in the Tcm, Tem, Tn, and Teff cells from the blood of lung cancer patients is lower than that of healthy donors." (PMID 28101811, 2017). "The molecular mechanism of urethane-induced lung cancer based on integration of TNF signals with NF-кB that accelerate tumor progression." (PMID 28240047, 2017). "SAHA also enhanced apoptotic effect of TNF-α in human lung cancer cells through up-regulation of TNFR1." (PMID 28099148, 2017). "Some cytokines have two opposite effects in lung cancer progression, according to the molecular context, which is the case for IL-10 and TNF-α." (PMID 27445423, 2016). "Inactivation of TNF-α-ATM-ERK/p38-NF-κB decrease lung cancer metastasis, providing advanced evidences for ATM inhibitor usage in lung cancer treatment." (PMID 27556690, 2016). "Circulating MAIT cell levels were significantly reduced in patients with mucosal-associated cancers (MACs), such as gastric, colon and lung cancers, but their capacities for IFN-γ, IL-17, or TNF-α production were preserved." (PMID 27517754, 2016). "In the present study, we demonstrated that TNF-α promoted lung cancer cell migration by up-regulation of matrix metalloproteinase-13 (MMP-13)." (PMID 27556690, 2016). "Deletion of RelA largely inhibited cigarette smoke-induced TNF-α production in macrophages as well as TNF-α-mediated β-catenin activation and lung cancer cell growth in mice." (PMID 27713747, 2016). "TNF-α was identified as the major host-produced factor that enhances the growth of metastases in the lung cancer animal model, in part through activation of NF-kB in the tumor cells." (PMID 27389279, 2016). "Some of these cytokines (IL-6, IL-8, IL-10, IL-22, VEGF, TGF-β, and TNF-α) have also been studied to determine their role in lung cancer and are described in comparison to other cytokines next." (PMID 27445423, 2016). "Reports have indicted that miR-224-3p can promote the proliferation and metastasis of lung cancer cells by inhibiting TNF-α-induced apoptosis." (PMID 27615604, 2016). "TNF-α IHC determination of lung cancer metastasis test showed that TNF-α expression in cancer nests and surrounding tissues was decreased by the depletion of ATM." (PMID 27556690, 2016). "Our data demonstrate that S100A4 drives the invasive capacity of lung cancer cells, affects the NF-κB pathway, and acts as an essential component of TNF-α-induced and NF-κB-dependent MMP9 expression." (PMID 27127879, 2016).
lung carcinoma (continued). "Despite that ataxia-telangiectasia mutated (ATM) is involved in IL-6 promoted lung cancer chemotherapeutic resistance and metastasis, the exact role of ATM in tumor necrosis factor-alpha (TNF-α) increasing tumor migration is still elusive." (PMID 27556690, 2016). "As cell viabilities had not been affected by above treatments, our data demonstrate that there is a positive correlation between TNF-α level and cell migration in lung cancer cells." (PMID 27556690, 2016). "In this latest study, authors compared levels of TNFα and vascular endothelial growth factor in patients with pneumonia and lung cancer, as well as healthy controls, while we evaluated a wide range of cytokines in a homogenous model such as CAP." (PMID 28702287, 2016). "Here, we found that TNF-α promote lung cancer metastasis by MMP-13 up-regulation and ATM activation." (PMID 27556690, 2016). "As ATM-NF-κB pathway is involved in IL-6-increased cell migration, we next explored the role of ATM-ERK/p38-NF-κB activation in TNF-α promoting lung cancer cell migration." (PMID 27556690, 2016). "To expand this analysis we used a multiplex laser bead assay to assess the effect of UNC1999 on LPS or TNFα induced production of multiple cytokines in A549 lung cancer cells." (PMID 26030458, 2015). "Three prominent cytokines produced in the COPD are TNF-α, IL-1, and IL-6, and these all also have important roles in lung cancer." (PMID 26220864, 2015). "TNFα induces IL-8 and IL-1β synthesis and secretion from adenocarcinoma lung cancer cells, Calu-3 cells." (PMID 26594334, 2015). "For this, we treated A549 lung cancer cells with TNFα, IL1β, E. coli lipopolysaccharide (LPS), as well as IFNγ, and assessed secretion of the cytokines CXCL10, IL6 and IL8." (PMID 26030458, 2015). "Previously a bystander effect mediated by TNF-α has been described in lung cancer cells treated with CM from 10 Gy relative to 2 Gy irradiated cultures." (PMID 24465461, 2014). "One previous study found that TAS was positively correlated with proinflammatory cytokines IL-1α, IL-6, and TNF-α in bronchoalveolar lavage fluid in lung cancer patients." (PMID 25254081, 2014). "Increased TNF-α and IL-1 secretion from AMs of patients with lung cancer after stimulation with IFN-γ and granulocyte-macrophage colony-stimulating factor (GM-CSF) has been demonstrated in comparison with patients with nonmalignant disorders." (PMID 26316944, 2014). "Impaired cytotoxic ability of AMs from patients with lung cancer has been shown along with increased TNF-α and IL-1 production in the same patients." (PMID 26316944, 2014). "The knockdown of ZFC3H1 reduced IL-8 expression levels in the TNFα-stimulated lung carcinoma cell line, LU99, and UV-irradiated HeLa cells." (PMID 25268596, 2014). "Based on the TNF-α-mediated genes found in the murine models, we developed a prognostic gene signature that effectively predicted recurrence-free survival in lung cancer in two validation cohorts." (PMID 25548907, 2014). "A number of pro- and/or anti-inflammatory cytokines have been described as possessing dual roles in lung cancer including TNFα, IL-6, IL-8, IL-10, VEGF, and PDGF." (PMID 26316944, 2014). "Despite these findings, decreased TNF-α secretion by AMs has also been reported in lung cancer patients." (PMID 26316944, 2014). "We found that, while RASSF1A overexpression induced MST1/2 phosphorylation, RASSF1C overexpression attenuated MST1/2 phosphorylation in breast and lung cancer cells after TNF-α treatment." (PMID 24327924, 2013). "Knockdown of Bcl-2 by siRNA also led to a significant increase in TNF-α-induced apoptosis, consistent with the previous finding that Bcl-2 is the major survival factor in lung cancer cells." (PMID 23339680, 2013). "The present study demonstrated that TGF-β and TNF-α synergically induces EMT in A549 lung cancer cells." (PMID 23437179, 2013).
lung carcinoma (continued). "Recent studies also mention that A. sinensis has the ability to suppress the expression of TGF-β1 in lung cancer study and the expressions of TNF-α and IL-6 in chronic inflammatory diseases." (PMID 24069047, 2013). "We found that while RASSF1A reduced cell proliferation and further enhanced the antiproliferative effects of TNF-α, RASSF1C significantly increased cell proliferation and reduced the antiproliferative effects of TNF-α on breast and lung cancer cells." (PMID 24327924, 2013). "Following TNF-α treatment of 20 ng/ml for 24 h, we have detected 30% of apoptosis in lung cancer A549 cells, during which, NF-κB transactivation function was significantly stimulated." (PMID 23339680, 2013). "The result indicated TNF-α treatment resulted in SLUG induction in lung cancer cell lines via NF-κB activation." (PMID 23339680, 2013). "In the study, we designed to investigate the effect of TNF-α on the activation and expression of nuclear factor kappa B (NF-κB)/p65/SLUG/PUMA/Bcl-2 levels in human lung cancer A549 cell line, and in conditions of TNF-α-induced apoptosis." (PMID 23339680, 2013). "Weight loss, lean body mass decrease, and hypermetabolism are highly correlated to both the elevated levels of proinflammatory cytokines, such as IL-1β, IL-6 and TNF-α and the decreased level of albumin in lung cancer patients." (PMID 23349693, 2013). "Our study suggested TNF-α treatment promotes apoptosis through the NF-κB-dependent PUMA pathway at an early time in lung cancer A549 cells." (PMID 23339680, 2013). "Consistent with this, we found that caspase 3/7 activation was significantly increased in breast and lung cancer cells overexpressing RASSF1A which were treated with TNF-α compared to those overexpressing RASSF1C." (PMID 24327924, 2013). "Overexpression of RASSF1C in breast and lung cancer cells reduced the effects of TNF-α on cell proliferation, apoptosis, and MST1/2 phosphorylation, while overexpression of RASSF1A had the opposite effect." (PMID 24327924, 2013). "More importantly, our data show that RASSF1C reduced while RASSF1A enhanced the antiproliferative effects of TNF-α on breast and lung cancer cells." (PMID 24327924, 2013). "Recent studies have shown that TNF-α enhances TGF-β-mediated EMT in lung cancer/epithelial cells, suggesting the potential crosstalks between these signals." (PMID 23437179, 2013). "In the present study, we investigated the effect of TNF-α on apoptosis in lung cancer A549 cells, and explored its mechanism." (PMID 23339680, 2013). "A normal human bronchial epithelium cell line (NuLi-1) and three lung cancer cell lines (MS-1, A549, and LK-2) were treated with TNF, 17-DMAG, or both of them together for 24 hour or 48 hours." (PMID 23635099, 2013). "Thirty percent of apoptosis was detected in lung cancer cells following 20 ng/ml of TNF-α treatment for 24 h." (PMID 23339680, 2013). "One of the novel findings of the present study is the evidence that in human lung cancer A549 cells TNFα alone induced morphological changes, stress fiber formation, cell migration and the alteration of gene expression." (PMID 22675434, 2012). "In the present study, human lung carcinoma A549 cells were treated with TNFα and TGFβ1 to induce EMT." (PMID 22675434, 2012). "In summary, we found that TNFα stimulation induces the gene expression of Claudin 1 in human lung cancer cells, and the latter acts as the signal mediator to regulate gene expression and cell migration." (PMID 22675434, 2012). "CDA-2 and PG significantly reduced NF-κB DNA-binding activity in lung cancer cells and in alveolar macrophages of tumor bearing mice and especially decreased the release of inflammatory factors including TNFα, IL-6, and KC." (PMID 23284890, 2012). "To investigate EMT in human lung carcinoma A549 cells, we treated cells with TNFα (20 ng/ml) and TGFβ1 (10 ng/ml) for 72 h." (PMID 22675434, 2012).
lung carcinoma (continued). "Monocytes activated by tumour-derived microvesicles from pancreatic, colon and lung cancer cell lines have been found to show increased expression of HLA-DR and a resulting increase in production of reactive oxygen intermediates and TNFα." (PMID 21799753, 2011). "Comparison of the cytostatic and cytotoxic effect of TNF-α against a wide range of tumor types demonstrated that approximately a quarter of tumors (28%) are sensitive to the effects of TNF-α and that this sensitivity was greater in colorectal and lung cancers." (PMID 22036896, 2011). "Previous studies by our group have shown that A549 lung cancer cells can be sensitized to TNF by AdIKKβKA or AdIkBαSR expression." (PMID 20977779, 2010). "To understand the molecular mechanisms involved in TNFα-induced optineurin gene expression we used human lung carcinoma cell line A549 which is responsive to TNFα." (PMID 19340308, 2009). "Adenovirus-mediated delivery of IKKβ (Ad.IKKβKA) or IkBα (Ad.IkBαSR) dominant negative mutants have previously been demonstrated to sensitize lung cancer cells to TNF death ligand." (PMID 15916713, 2005). "For this study, we collected and analyzed the correlation between clinical data and levels of serum inflammatory cytokines (interleukin [IL]-2, IL-6, IL-8, and tumor necrosis factor [TNF]-α) to guide the prognosis of patients who suffered advanced-stage lung cancer." (PMID 40265008, 2025). "In conclusion, rutin enhances TNF-α-induced apoptosis of A549 human lung carcinoma cells." (PMID 41142938, 2025). "In addition, exposure of lung cancer cells to IL-4 suppressed the increase in TAP2 protein induced by IFNγ or IFNγ + TNFα." (PMID 40091029, 2025). "In previous scientific research, elevated levels of TNF expression have been observed in lung cancer and may play a tumorigenic role." (PMID 40149878, 2025). "Nevertheless, among patients receiving TNF inhibitors, those with a history of lung disease or smoking had a potentially heightened risk of lung cancer when compared to those on non-biologic DMARDs." (PMID 40282506, 2025). "Similarly, EGFR tyrosine kinase inhibitor (erlotinib) treated lung cancer cells downregulated miR21, which regulates the TNF and NF-κB signaling in mutant EGFR cells." (PMID 39948411, 2025). "Clinically, elevated TNF-α predicts poorer survival in colorectal, breast, and lung cancers." (PMID 41473193, 2025). "The inflammatory microenvironment also promotes the progression and metastasis of lung cancer, and TNF-α CRP and IL-6 are common inflammatory factors, and their serum levels are generally elevated in lung cancer patients and are significantly correlated with tumor activity." (PMID 38957318, 2024). "Many studies have shown that mechanisms of action by DNTs to kill AML or lung cancer cell lines via various innate receptors, such as NKG2D and DNAM‐1, and releasing cytotoxic factors such as IFN‐γ and TNF‐α, thereby making target cells more susceptible to their cytotoxic activity." (PMID 39720695, 2024). "Additionally, TNF-α, IL-6, and IL-1β induce elevated Ido1 expression in the context of immunosuppression in lung cancer progression." (PMID 39759510, 2024). "Given that lung cancer cells also secrete IL-6 and TNF-α, it is speculated that lung cancer cells and BMAs, by regulating OB function and inhibiting osteogenic differentiation, indirectly disrupt bone remodeling and promote lung cancer bone metastasis." (PMID 38571500, 2024). "TNFα studies have highlighted its potential for use as a highly specific anticancer drug in the treatment of a wide variety of tumors, especially colorectal and lung cancers." (PMID 38195677, 2024). "We examined eight key cytokines (Interleukin-1, IL-6, IL-8, IL-10, IL-12p70, monocyte chemotactic protein-1 (MCP-1), interferon-gamma (IFN-γ), and tumor necrosis factor-alpha (TNF-α)) in the plasma of 104 lung cancer patients and 48 cancer-free individuals using the FirePlex Immunoassay." (PMID 38276239, 2024).
lung carcinoma (continued). "Additionally, the ROC curve indicated that combination of MIP-1α, MIP-1β, and TNF-α is a good predictor to the early stage of lung cancer." (PMID 38813211, 2024). "Additionally, endurance exercise downregulates TNF-α and iNOS expression in lung cancer tissue but upregulates IL-6 and IL-10 expression." (PMID 37691942, 2023). "Studies have reported that R.gnavus inhibits TNF-α secretion and may suppress lung cancer metastasis." (PMID 37577375, 2023). "These two pathways suggest the provocative idea that patients with early-stage lung cancer may benefit from neoadjuvant therapy after their tumors are resected, such as TNF-α blockers or IL-17 inhibitors." (PMID 37938580, 2023). "Moreover, it has been reported that BA reverses the formaldehyde-induced increase in TNF-α in human lung cancer cells." (PMID 37772231, 2023). "Blockade of TNFα signaling can render lung cancer PDXs that express wild-type EGFR sensitive to the treatment of EGFR inhibitors, and improve the therapeutic effect of EGFR inhibitors in lung cancer PDXs with EGFR mutations." (PMID 36923932, 2023). "However, it has been reported that SOR reduces JNK expression in lung cancer cell lines in vitro, and it has therapeutic properties by reducing TNF-α and IL-1β levels in liver cancer." (PMID 37259369, 2023). "Rutin promotes the apoptosis of TNF-α-induced A549 human lung cancer cells." (PMID 37189139, 2023). "Lastly, TNF-alpha did not significantly affect lung cancer risk, with an odds ratio of 1.19 (95% CI: 0.94–2.38, p = 0.118) for patients with levels above 34 pg/mL." (PMID 37373957, 2023). "Interestingly, it has been shown that there is upregulation of the key components of immune response to infection, NFκB or TNF, in cisplatin-resistant lung cancer cell lines." (PMID 37210583, 2023). "The results ultimately suggested that determining BAL fluid TNF-α levels in flexible bronchoscopy may be unhelpful in diagnosing lung cancer." (PMID 37373987, 2023). "Additionally, it was found that the S1 protein of SARS-CoV-2 can activate the NF-κB signalling pathway in lung cancer cells, increase the expression of proinflammatory factors such as TNF-α, and thus induce lung cancer cell death." (PMID 37033918, 2023). "Animal studies demonstrated that aerobic exercise could reduce lung cancer inflammation, increase the levels of the anti-inflammatory cytokine IL-10, and decrease the levels of pro-inflammatory cytokines (such as TNF-α, IL-6, and IL-1)." (PMID 37691942, 2023). "An examination of the Cancer Genome Atlas database shows that for lung cancer, IL-1 and TNF reveal a tendency as an oncogene, as patients with higher IL-1β and TNF-α mRNA levels are linked to shorter overall survival, although this correlation does not reach statistical significance." (PMID 37259369, 2023). "TNF-α acts as either a tumor suppressor or promoter in lung cancer." (PMID 36140220, 2022). "In addition, we found that endurance exercise significantly decreased the mRNA levels of CD86, TNF-α, and iNOS in lung cancer tissues." (PMID 36186906, 2022). "We aim to describe the characteristics of hepcidin, IL-6, and TNF-α levels in anaemia of lung cancer patients with operative tumour as well as to investigate the potential diagnostic capabilities of hepcidin in combination with IL-6, TNF-α, and acute phase proteins." (PMID 36612220, 2022). "Indeed, we found that expression of IL-1β, IL-6 and TNFα was dramatically reduced in lung cancer cells in response to BAY11-7082 treatment." (PMID 36457047, 2022). "We were only able to detect TNF-α and IL-6, implying that these two cytokines could be mainly involved in S1P-mediated inflammatory signaling in lung cancer-derived PBMCs." (PMID 36010601, 2022). "In our study, CRP levels and TNF-α levels were significantly decreased, suggesting that ω-3 PUFAs may have some regulatory effect on the inflammatory status in patients treated with lung cancer radiotherapy and chemotherapy." (PMID 35910071, 2022).